RAD51 (RAD51 recombinase)
Diseases named in the same sentence as RAD51 in open-access papers (continued):
Sharing a sentence is not in itself a finding about the gene and the disease.
prostate carcinoma (continued). "Specifically, AR antagonists demonstrate contextual synthetic lethality with PARPi by modulating the expression of key HR proteins such as BRCA1/2 and RAD51, and potentially enhance the vulnerability of prostate cancer cells on alternative DNA repair mechanisms, such as PARP-mediated repair." (PMID 37812088, 2023). "Overall, these findings suggest that ivermectin could block NHEJ repair by targeting Ku70/Ku80 and HR repair by downregulating the expression of BRCA1 and Rad51, thereby triggering synthetic lethality in AR-positive prostate cancer cells." (PMID 36050295, 2022). "Moreover, STAT5A/5B participated in the regulation of DNA repair using homologous recombination in prostate cancer by inducing the RAD51 mRNA level while blocking of JAK2-STAT5A/5B signal pathway sensitized prostate cancer to radiotherapy." (PMID 36524006, 2022). "Stat5a/b is a critical inducer of RAD51 and HR DNA repair in prostate cancer." (PMID 34716319, 2021). "KRAS has been characterized as a cancer-related gene with potential importance for future cancer treatment, while RAD51 and XRCC3 polymorphisms may be associated with an increased risk of prostate cancer." (PMID 33240468, 2020). "Furthermore, veliparib treatment (another type of PARPi) of PTEN-null PC3-AR prostate cancer mouse xenografts has been shown to enhance RAD51 expression and HR activity under hypoxic conditions and reduce chemotherapy-mediated DNA damage and cell apoptosis." (PMID 33138032, 2020). "Our study has shown the importance of RAD51 and its paralog XRCC3 polymorphism in prostate cancer." (PMID 31186630, 2019). "Indeed in prostate cancers cells, suppression of RAD51, the recombinase that catalyses the strand invasion step of HR, sensitises cells to IGF-1R inhibition." (PMID 27472395, 2016). "The aim of the present study was to evaluate the relationship between prostate cancer risk and the presence of single nucleotide polymorphisms (SNPs) in the genes involved in HRR, that is, RAD51 (rs1801320 and rs1801321), RAD51B (rs10483813 and rs3784099), XRCC2 (rs3218536), and XRCC3 (rs861539)." (PMID 26339569, 2015). "However, while control (siNEG) cells form Rad51 foci indicative of HR-mediated repair, cells with siRNA-mediated depletion of PALB2 or BARD1 resemble BRCA2-deficient cells and fail to form Rad51 foci, suggesting that PALB2 or BARD1 loss is sufficient to confer HR deficiency in prostate cancer cells." (PMID 35768576, 2022). "Our results indicate that RAD51 and XRCC3 polymorphism may contribute to prostate cancer." (PMID 31186630, 2019). "Hence, the aim of the present study is to determine whether loss of heterozygosity (LOH) in RAD51, BRCA1, and BRCA2 contributes to the sporadic prostate cancer." (PMID 26433958, 2015). "Vimentin and RAD51 expression also showed a trend to positively correlate, in line with the fact that RAD51 is coupled with EMT in breast and prostate cancer." (PMID 40456663, 2025). "Further, inhibition of BET proteins also led to attenuation of RAD51 and BRCA1 proteins in breast, ovarian, and prostate cancer models." (PMID 37370140, 2023). "Specifically in prostate carcinoma cell lines DU145 and PC-3, EGFR inhibitors were utilized to downregulate the expression of RAD51, potentiating the effects of ionizing radiation on cell proliferation." (PMID 38001574, 2023). "Genetic and genomic scores are being considered concurrently with RAD51 foci determination as biomarkers predictive of treatment in TNBC and prostate cancer." (PMID 37007122, 2023).
prostate carcinoma (continued). "RAD51 overexpression is observed in several cancers, including pancreatic, soft tissue sarcoma, breast, NSCLC, prostate cancer, glioblastoma and leukemia." (PMID 35463312, 2022). "SPOP knockdown in various prostate cancer cell lines (e.g., C4-2b cells, PC3 cells, LNCap cells, 22Rv1 cells) or U2OS cells reduced the mRNA and protein expression of ATR, BRCA2, ChK1, and Rad51." (PMID 33023230, 2020). "Similar non-correlative findings have also been reported in a separate primary prostate cancer TMA, and further work has shown that RAD51 recruitment to DSBs in prostate cancer cells in response to UV irradiation is not impeded by PTEN deficiency." (PMID 33105713, 2020). "The purpose of the presented work was to investigate further selected single nucleotide polymorphisms (SNPs), i.e., rs2619679, rs2928140, and rs5030789 in RAD51 and rs1799796 in RAD51 paralog XRCC3 and their relationship to prostate cancer." (PMID 31186630, 2019). "In prostate cancer cells, co-inhibition of epidermal growth factor receptor and IGF-1R reduced phosphorylation of IRS-1 and its interaction with RAD51, suppressing HR and increasing radio-sensitivity." (PMID 26510816, 2015). "The combination of vorinostat with olaparib synergistically reduced prostate cancer cell viability, induced apoptosis in DU145 and PC3 prostate carcinoma cells, and suppressed DNA repair as well as DNA repair protein expression (BRCA1 and RAD51) in DU145 cells." (PMID 35582529, 2022). "Among all these inhibitors, DIDS effect against RAD51 activity was demonstrated very early but this molecule is relatively cytotoxic in fibroblast and prostatic cancer cells (data not shown), weakly specific, and was proved to be unstable in aqueous solution." (PMID 34576930, 2021). "Although germline mutations and LOH in BRCA1 and BRCA2 genes have been detected in mutation carriers, no data currently exist concerning the role of RAD51 in sporadic prostate cancer." (PMID 26433958, 2015). "• Enhances HR activity, D-loop formation and the formation of toxic RAD51 complexes on undamaged chromatin.• Leads to the accumulation of RAD51 foci in prostate cancer cells but not in normal cells which is independent of DNA damage.• Enhances cellular resistance to cisplatin at ~7.5 μM." (PMID 35463312, 2022). "However, other findings have not supported these results, showing no impact on RAD51 expression and foci formation by PTEN deficiency, and only mild sensitivity of PTEN-deficient cells to PARP inhibition in primary prostate cancer cell lines and xenografts." (PMID 27375368, 2016). "However, although an association between RAD51 deficiency, impaired HR and PTEN deficiency has been demonstrated in colorectal cancer cells and endometrial cancer cells, the association was not demonstrated in prostate cancer models." (PMID 24830350, 2014).
lung carcinoma (62 papers, 2005 to 2025). "Analysis of tumor samples revealed that BRCA1 and RAD51 levels were elevated in FHIT-deficient lung cancer, and CHIR99021 treatment reduced their protein levels." (PMID 39762409, 2025). "Additional functional experiments revealed that USP9X-deficient lung cancer cells formed longer comet trails, fewer Rad51 foci, and exhibited enhanced radiosensitivity after radiation exposure." (PMID 38802791, 2024). "Several studies have shown that RAD51 expression is associated with resistance to radiotherapy and chemotherapy in osteosarcoma and lung cancer cells." (PMID 37798649, 2023). "On the other hand, RAD51 rs1801320 was associated with radiation pneumonitis in lung cancer and radiochemotherapy-induced acute toxicity in rectal cancer." (PMID 36139526, 2022). "The KM Plotter Online Tool (kmplot.com) was used to associate RAD51 expression with clinical outcome for more than 1000 patients with breast or lung cancer." (PMID 35646698, 2022). "It has been proved that Rad51 G135C allele is associated with a higher survival time and a better prognosis in lung cancer patients treated with platinum-paclitaxel / gemcitabine Wrst line chemotherapy." (PMID 36384536, 2022). "In lung cancer, high expression of Rad51 in tumor tissue is associated with an unfavorable prognosis." (PMID 26316936, 2012). "Next, we performed in vitro experiments using conditioned media with depletion of specific amino acids and found that after radiation treatment, REV1-deficient lung cancer cells exhibited extended comet tails, a reduced number of Rad51 foci, and increased radiosensitivity." (PMID 38802791, 2024). "Increased preference for HR in response to PBT was observed through enhanced cellular radiosensitivity of RAD51-depleted lung carcinoma cells, associated with delays in resolving of γH2AX foci, but also in osteosarcoma cells through persistence in RAD51 and RPA foci." (PMID 38368415, 2024). "Another study found that ATM inhibition or loss of FANCD2 conferred a reduction in HRR and RAD51 foci formation in lung cancer, which is consistent with our finding that complete ATM loss in NGP cells impaired HRR through the downregulation of FANCD2 and RAD51 expression." (PMID 37020276, 2023). "Interestingly, downregulation of the receptor tyrosine kinase AXL has been suggested to enhance the response of HNSCC cells (584 and 1386-LN), as well as breast and lung cancer cells, to olaparib and which was linked with reduced levels of RAD51 foci and decreased HR efficiency." (PMID 36052247, 2022). "We observed that geldanamycin partially induced synthetic lethality with FHIT loss in lung cancer cells, accompanied by the downregulation of BRCA1 and RAD51 levels." (PMID 39762409, 2025). "We showed that a GSK3β inhibitor selectively inhibited FHIT-deficient lung cancer by inhibiting the ATR/BRCA1/RAD51 signaling axis and BRCA1/RAD51 transcription, leading to the inhibition of HRR and genotoxic cell death." (PMID 39762409, 2025). "All FHIT-deficient lung cancer cells presented increased expression levels of BRCA1 and RAD51 and increased levels of phosphorylated DNA-PKcs." (PMID 39762409, 2025). "To rule out off-target effects of a particular ATR inhibitor, we confirmed the effects of ATR inhibition using a different ATR inhibitor in our lung cancer models for clonogenic cell survival and RAD51 foci formation." (PMID 39235982, 2024). "Overall, our results demonstrate that deguelin can inhibit the function of FBXO22 and enhance lung cancer radiosensitivity in a Rad51-dependent manner." (PMID 38296976, 2024). "Collectively, FBXO22 increases the level of FOXM1 at the Rad51 promoter, which in turn enhances the transcriptional activity of Rad51 and ultimately leads to lung cancer radioresistance." (PMID 38296976, 2024).
lung carcinoma (continued). "Consistent with the database results, FOXM1 was downregulated upon FBXO22 silencing and promoted Rad51 expression at the transcriptional and translational levels in lung cancer cells." (PMID 38296976, 2024). "This suggests that Rad51 is essential for the development of FBXO22-induced lung cancer radioresistance." (PMID 38296976, 2024). "Mechanistically, FBXO22 promoted Rad51 gene transcription by increasing the level of FOXM1 at the Rad51 promoter, thereby inducing the formation of lung cancer radioresistance." (PMID 38296976, 2024). "Mechanistically, FBXO22 promoted Rad51 gene transcription by increasing the level of FOXM1 at the Rad51 promoter, which contributes to insensitivity to lung cancer radiotherapy." (PMID 38296976, 2024). "Collectively, our results illustrate that FBXO22 induces lung cancer radioresistance by activating the FOXM1/Rad51 axis and provide preclinical evidence for the clinical translation of this critical target." (PMID 38296976, 2024). "CDK1 and CDK12 inhibition led to HR deficiency by decreasing HR repair proteins RAD51, BRCA1, and BRCA2 in lung cancer." (PMID 37370140, 2023). "Elevated RAD51 expression in lung cancer patients has been shown to correlate with their poor survival." (PMID 36428789, 2022). "An early clinical study showed that, for lung cancer patients, overexpression of RAD51 resulted in significantly worse survival, which inferred the potential prognostic value of RAD51 for cancer patients." (PMID 35359409, 2022). "Elevated RAD51 expression in lung cancer patients has also been shown to correlate with their poor survival." (PMID 36428789, 2022). "Our results showed a strong combination effect of RAD51 inhibitors and cisplatin in A549 lung cancer cells." (PMID 35646698, 2022). "Previous studies on lung cancer have shown that the inhibition of RAD51 expression can reduce the HR repair ability of cancer cells and increase their sensitivity to chemotherapy and radiotherapy." (PMID 34575923, 2021). "This would contradict some very limited evidence suggesting a greater dependence on the HR pathway mediated by ATR for repairing DNA DSBs induced by protons, which was obtained using RAD51 siRNA in A549 lung cancer cells." (PMID 32517381, 2020). "A similar study also revealed that lung cancer patients harboring a strong Rad51 expression had a significantly poorer survival than those without a Rad51 expression." (PMID 31973027, 2020). "A similar increase in RAD51 levels after cisplatin treatment has been reported in lung cancer cell lines." (PMID 29254481, 2017). "A first interesting observation about these genes is that many of them have been positively implicated in breast and/or lung cancer progression and resistance to therapy: AURKA, CAV2, RAB27A, RAD51, TIMELESS, TIMM17A." (PMID 22347440, 2012). "In contrast, overexpression of Rad51 protects lung cancer cells from the synergistic cytotoxic effects induced by mitomycin C and emodin (1,3,8-trihydroxy-6-methyl-anthraquinone)." (PMID 26316936, 2012). "Gefitinib, a selective epidermal growth factor receptor tyrosine kinase inhibitor, was found to downregulate RAD51 in lung cancer cells and sensitize them to mitomycin C and gemcitabine." (PMID 21858113, 2011). "In contrast, emodin, a substance found in some plants including rhubarb, was reported to inhibit the activation of ERK1/2 in lung cancer cells, which in turn leads to a downregulation of RAD51 and confers chemosensitivity." (PMID 21858113, 2011). "The results revealed that both wild-type and hydrolase-dead mutant FHIT successfully reduced the BRCA1 and RAD51 protein levels in FHIT−/− lung cancer cells, suggesting that the Ap3A hydrolase activity of FHIT is not crucial for HRR protein stability or DNA damage repair signaling." (PMID 39762409, 2025).
lung carcinoma (continued). "Tumor patients with high Rad51 expression tend to experience poor radiotherapy response, whereas pharmacological inhibition of Rad51 dramatically increases radiosensitivity in prostate, breast, and lung cancers." (PMID 38296976, 2024). "Therefore, we conclude that FBXO22 upregulates the expression of FOXM1 and FOXM1 directly binds to the Rad51 promoter to transactivate Rad51, which ultimately leads to lung cancer radioresistance." (PMID 38296976, 2024). "Thus, FBXO22 is likely to activate HR through the upregulation of Rad51, thereby leading to lung cancer radioresistance." (PMID 38296976, 2024). "Intriguingly, knockdown of endogenous Rad51 could suppress the growth of the A549 lung cancer cells through accumulation of cells in G1 phase and induction of cell death, thereby serving as an independent prognostic gene in patients with NSCLC." (PMID 36793108, 2023). "Consistent with the neutral comet assay, DNA damage-induced Rad51 foci formation was drastically decreased when UBE2O was knocked down, indicating that loss of UEB2O can accelerate DNA damage and impair DNA repair in lung cancer." (PMID 32901121, 2021). "Rad51 can protect lung cancer cells from cytotoxic effects induced by gefitinib." (PMID 26316936, 2012). "Suppression of Rad51 expression by small interfering RNA (si-Rad51 RNA) transfection can augment the cytotoxic effect of gefitinib, suggesting that Rad51 may be a novel lung cancer therapeutic modality to overcome drug resistance to gefitinib." (PMID 26316936, 2012). "Previous studies found some potentially functional SNPs of HR genetic polymorphisms (e.g., RAD51-135 G>C, −172G>T, XRCC2 4234G>C, R188H, XRCC3 T241M and NBN E185Q) to be associated with various types of cancer risks, including cancers of the lung, breast, ovary, leukemia and head and neck." (PMID 21647442, 2011). "Known lung cancer genes (EGFR, KRAS G12C, ALK, MET, RET) were found in 33 patients; 11 had genes relevant to both lung and other cancers (ERBB2, BRAF V600, NTRK), and 37 had genes typically linked to other malignancies (NF1, PIK3CA, PALB2, FGFR2B, FBX7, RAD51)." (PMID 40244261, 2025). "In addition, the FOXM1/Rad51 axis protect lung fibroblasts from radiation-induced cell death, indicating that this axis may be involved in lung cancer radiosensitivity." (PMID 38296976, 2024). "In KRAS-mutant lung cancer cells, RAD51 may facilitate DNA damage repair and promote cell survival." (PMID 36164607, 2022). "Thus, suppression of Rad51 expression may be considered as potential therapeutic modalities for lung cancer." (PMID 26316936, 2012). "To confirm this conjecture, we designed wild-type and mutant luciferase reporter plasmids based on the binding site of FOXM1 to the Rad51 promoter and detected the luciferase activity after co-transfecting them with siRNA targeting FOXM1 in lung cancer cells." (PMID 38296976, 2024). "To clarify the effects of ATR inhibition specifically on DNA repair pathways, we tested the effects of AZD6738 on HR by investigating RAD51 formation in NCI-H460 and NCI-H1299 lung cancer cells." (PMID 39235982, 2024). "Clonogenic survival assays, neutral comet assays, Rad51 foci formation assays, and Annexin V/propidium iodide assays were used to determine the significance of FBW7/IGF2BP2/SLC7A5 axis in lung cancer radioresistance." (PMID 38281999, 2024). "In summary, FBXO22 increases the expression of Rad51 in a FOXM1-dependent manner, which in turn triggers lung cancer radioresistance." (PMID 38296976, 2024). "Mechanistically, FBXO22 facilitated transcriptional activation of the homologous recombinase Rad51 through upregulation of the transcription factor FOXM1, thus promoting DNA damage repair and lung cancer radioresistance." (PMID 38296976, 2024). "FBXO22 is aberrantly highly expressed in lung cancer and participates in radioresistance formation by activating the FOXM1/Rad51 axis." (PMID 38296976, 2024).